RNU7-75P (RNA, U7 small nuclear 75 pseudogene)
Synonyms: U7.75
Gene: Small nuclear RNA gene on chromosome 5 (37,327,135 to 37,327,196, forward strand). Ensembl gene ENSG00000251880.
Homologues: Orthologues: macaque U7 (90% identical), rabbit U7 (79% identical). Paralogues in human: RNU7-34P (84% identical), RNU7-1 (82% identical), RNU7-24P (82% identical), RNU7-26P (82% identical), RNU7-2P (82% identical), RNU7-37P (82% identical), RNU7-56P (82% identical), RNU7-73P (82% identical), RNU7-7P (82% identical), RNU7-11P (81% identical), RNU7-124P (81% identical), RNU7-13P (81% identical), and 142 more.